ITGB1 (integrin subunit beta 1)
Diseases named in the same sentence as ITGB1 in open-access papers (continued):
Sharing a sentence is not in itself a finding about the gene and the disease.
cervical carcinoma (continued). "Moreover, we further explored whether KLF14 regulates ITGB1 and plays an inhibitory role in the progression of cervical cancer by regulating the PI3K/AKT signalling pathway." (PMID 35570248, 2022). "As a part of the pathway involved in extracellular matrix-receptor interactions, ITGB1 exhibits a remarkable increase in expression in HPV-related head and neck cancer (HNC), cervical cancer (CC), and patients with OCSCC." (PMID 40821990, 2025). "Previous studies of my research group found that KLF14 targets ITGB1, promotes apoptosis through the PI3K/AKT signaling pathway, and inhibits the progression of cervical cancer." (PMID 38143751, 2023). "ITGB1 also plays an important role in this process, as KLF14 inhibits the progression of cervical cancer by targeting ITGB1 through the PI3K/AKT signalling pathway." (PMID 35570248, 2022). "Moreover, ITGB1 inhibited apoptosis and reversed the effect of KLF14 on cervical cancer cell apoptosis." (PMID 35570248, 2022). "Therefore, we considered whether KLF14, ITGB1 and PI3K/AKT signaling pathways are correlated to affect the progression of cervical cancer." (PMID 35570248, 2022).
bladder cancer (13 papers, 2017 to 2025). "CD44 is related to tumor heterogeneous adhesion and other functions, while ITGB1 has been confirmed to be involved in the occurrence and development of gastric, pancreatic, and bladder cancers, and is closely related to cellular immunity and immunosuppression." (PMID 34931260, 2022). "Additionally, SPP1 can also recognize albumin (ALB), integrin-A (ITGAV) and integrin-B (ITGB1) proteins whose expression was found to be highly increased at an early stage of bladder cancer development, using the TCGA-BLCA search engine." (PMID 38067407, 2023). "The results revealed that bladder cancer cells secrete SPP1, which may interact with the integrin α4/β1 (ITGA4/ITGB1) complex of T cells to influence T cell function." (PMID 40665335, 2025). "Additionally, NRAS, EHD4, ITGB1 and MUC1, which were among the protein set correlating with bladder cancer on PCA, have been found in various studies of bladder cancer exosomes." (PMID 32249794, 2020).
non-small cell lung carcinoma (11 papers, 2017 to 2024). A group of at least three distinct histological types of lung cancer, including non-small cell squamous cell carcinoma, adenocarcinoma, and large cell carcinoma. "Correspondingly, the knockdown of ITGB1 increased the apoptotic rate and overexpression of ITGB1 led to radio-resistance in non-small cell lung cancer." (PMID 38814534, 2024). "It was demonstrated that ITGA5 and ITGB1 are prognostic in non-small-cell lung cancer by integrin and gene network analysis." (PMID 33414898, 2020). "High ITGB1 expression is also negatively correlated with the prognosis of patients with non-small cell lung cancer." (PMID 33335550, 2020). "Moreover, ITGB1 enhanced the radiotherapy resistance of human non-small cell lung cancer, while tumor progression was particularly noted in ITGB1-positive GC." (PMID 37667169, 2023).
liver cancer (10 papers, 2015 to 2025). An epithelial or non-epithelial malignant neoplasm that arises from the liver. "We further examined the ITGB1 expression (mRNA level) in tumor tissues from patients, and found increasing expression of ITGB1 in tumor tissues from liver cancer patients with a higher tumor matrix stiffness." (PMID 34823500, 2021). "Here, we found that high level of ITGB1 in liver cancer patients was related to a poor prognosis." (PMID 33803301, 2021). "By suppressing the expression of ITGB1, CSN5 deletion slows the proliferation of liver cancer cells." (PMID 39258668, 2024). "Additionally, high‐dose BBR regulated the interactions from liver cancer immune cells to CD8+ T cells via ligand‐receptor pairs such as CCL3–CCR5, CCL5–CCR5, CXCL6–CXCR6, and SPP1–(ITGA4+ITGB1)." (PMID 39135526, 2024). "Intriguingly, silence of ITGB1 in SMMC-7721 cells (low stiffness culture) showed limited effects on the cell proliferation, colony formation or cell migration, suggesting that high matrix promoted liver cancer development through an integrin β1 dependent manner." (PMID 34823500, 2021).
lymph node metastasis (10 papers, 2010 to 2025). "Higher ITGAV and ITGB1 expression were associated with lymph node metastasis and extrathyroidal extension, while ITGB6 expression positively correlated with lymph node metastasis, advanced stage, and extrathyroidal extension." (PMID 40423510, 2025). "In esophageal cancer, ITGB1 has been found to be associated with lymph node metastasis and poor prognosis, which can be used as an independent prognostic factor and confer resistance to chemotherapy in esophageal cancer." (PMID 38402311, 2024). "ITGB1 expression was associated with presence of lymph node metastasis (P = 0.039) and Integrin alpha V (ITGAV) expression (P < 0.001)." (PMID 36456612, 2022). "ITGB1 expression was associated with lymph node metastasis, expression of integrin alphaV and KRAS mutation status." (PMID 36456612, 2022). "Multivariate analysis performed with eight of these factors showed that ITGB1 expression, surgical procedure, nerve infiltration, T factor, and lymph node metastasis were independent prognostic factors." (PMID 35648752, 2022). "The expression of BMI1, ITGB1, and PXN-AS1 in 30 patients without lymph node metastasis was compared with 30 patients with lymph node metastasis, and only the expression of BMI1 and ITGB1 was further elevated in the tumor tissues of patients with lymph node metastasis." (PMID 38254031, 2024). "However, survival analysis of our ESCC patients revealed that increased ITGB1 expression was significantly associated with late TNM staging, worse prognosis and lymph node metastasis but with borderline significance." (PMID 26898710, 2016). "Furthermore, high expression of ITGB1 was correlated with late clinical stages in both cohorts (P = 0.019, P = 0.016, respectively) and with lymph node metastasis but with borderline significance (P = 0.057, P = 0.062, respectively)." (PMID 26898710, 2016). "The patients in the ITGB1 high-expression group were significantly older and had higher CA19-9 levels (p = 0.037 and 0.039, respectively), but other clinicopathological factors such as preoperative tumor marker levels and lymph node metastasis were not significantly different." (PMID 35648752, 2022).
nasopharyngeal carcinoma (9 papers, 2019 to 2026). A carcinoma arising from the nasopharyngeal epithelium. "Additionally, ITGB1 confers resistance to paclitaxel in nasopharyngeal cancer." (PMID 36293493, 2022). "Notably, ITGB1 was inversely correlated with miR-124-3p in nasopharyngeal carcinoma." (PMID 33299380, 2020). "It has also been reported that miR-9–3p can inhibit epithelial-mesenchymal transition by down-regulating ITGB1, FN1, and ITGAV in nasopharyngeal carcinoma." (PMID 31164410, 2019).
osteosarcoma (9 papers, 2010 to 2024). A usually aggressive malignant bone-forming mesenchymal neoplasm, predominantly affecting adolescents and young adults. "Our study found that ITGB1 regulates MMP2 expression, which modulates the malignant phenotype of osteosarcoma." (PMID 38664375, 2024). "In the low TELscore group, ITGB1 and CCL3L1 were the most active signaling pathways of cytokines in osteosarcoma cells." (PMID 39980969, 2024). "In the high TELscore group, LRP1, ITGB1, IBSP, COL1A1, and COL1A2 were the most active signaling pathways of others in osteosarcoma cells." (PMID 39980969, 2024). "PSO may suppress osteosarcoma via the FAK and PI3K/Akt signaling pathways by downregulating ITGB1 expression." (PMID 37004120, 2023).
triple-negative breast carcinoma (9 papers, 2016 to 2026). An invasive breast carcinoma which is negative for expression of estrogen receptor (ER), progesterone receptor (PR), and human epidermal growth factor receptor 2 (HER2). "Through a series of in vivo CRISPR screens, we identified tumor-intrinsic ITGB1 as a critical regulator of triple-negative breast cancer (TNBC) development and deciphered its underlying mechanisms." (PMID 41632816, 2026). "Knockdown of ITGB1 reduced the invasion and migration of Triple-negative breast cancer (TNBC) cells." (PMID 38963646, 2025). "In triple-negative breast cancer cells with high ITGB1 expression, suppressing ITGB1 enhanced IGF-1R stability and its retention at the plasma membrane, and reduced IGF-1R internalization during cell adhesion." (PMID 39608716, 2024). "ITGB1 has been identified as a potential prognosis biomarker in triple negative breast cancer." (PMID 27542231, 2016). "Reinforcing this; the most significant (p=3.5×10-25) individual marker of cluster 0res0.75 is ITGB1 (CD29, a well-documented breast SCLC cell marker), and of cluster 3res0.75 is HMGA1 (p=1.8×10-15), a driver of the stem-like state in triple negative breast cancer cells (Figure 5Biii)." (PMID 29796188, 2018).
breast tumor (8 papers, 2013 to 2025). "The results show that MUC1 and ITGB1 tended to have higher expression levels in brain metastases compared with primary breast tumors." (PMID 37108248, 2023). "In primary human breast tumors, the most common ITGB1 isoform 1 A was positively correlated to Suppressor-SFs such as DDX3X and DHX9 while being negatively correlated to Enhancer-SFs such as CCDC12 and FAM50A." (PMID 30940821, 2019). "In primary human breast tumors the most common ITGB1 isoform A1 was negatively correlated to Enhancer-SF genes, yet positively correlated to Suppressor-SF genes." (PMID 30940821, 2019). "In our hands, the expression of the ITGB1 isoform 1D in primary breast tumors was particular related to high expression of Enhancer-SFs." (PMID 30940821, 2019). "The spatial pattern of ITGB1 was identified in multiple other tissues, including bladder tumor, liver tumor, intestine, and breast tumor, consistent with the previous studies showing that it could be pro-tumorigenic by enhancing cell migration and stromal invasion." (PMID 36243975, 2023). "Analysis of RNA-seq databases showed significantly decreased FGFR2 and ITGB1 mRNA levels in breast tumour samples, when compared to non-transformed tissues." (PMID 37191822, 2023).
cholangiocarcinoma (8 papers, 2018 to 2024). A carcinoma that arises from the intrahepatic biliary tree (intrahepatic cholangiocarcinoma) or from the junction, or adjacent to the junction, of the right and left hepatic ducts (hilar cholangiocarcinoma). "ALDH3B2 promotes the proliferation and metastasis of cholangiocarcinoma by regulating ITGB1 expression." (PMID 38903532, 2024). "Moreover, expressions of six TF genes (SP1, CREB1, MAX, FHL2, RFX1, and HIF1A) was positively correlated with the expression of ITGA6 and ITGB1 in cholangiocarcinoma tissues." (PMID 34199886, 2021). "For example, cholangiocarcinoma (CHOL) overexpresses a large variety of subunits (e.g. ITGAV, ITGA1, ITGA4, ITGA5, ITGA11, ITGB1, ITGB2, ITGB6), whereas, the equally deadly pancreatic adenocarcinoma (PAAD) overexpresses a very limited set of integrins, including ITGA6 and ITGB4." (PMID 30046394, 2018).
head and neck squamous cell carcinoma (8 papers, 2019 to 2024). A squamous cell carcinoma that arises from any of the following anatomic sites: lip and oral cavity, nasal cavity, paranasal sinuses, pharynx, larynx, and salivary glands. "In head and neck squamous cell carcinoma cells, ectopic expression of the miR-29-3p-family inhibited ITGB1-mediated oncogenic signaling." (PMID 34199886, 2021). "For example, Integrin subunit beta 1 (ITGB1) regulates multiple pathophysiological signaling pathways and promotes metastasis of gastric, prostate, breast, and head and neck squamous cell carcinoma (HNSCC) cells." (PMID 32010630, 2019). "Additionally, ITGB1 interacts with Notch1 to regulate the stemness of head and neck squamous cell carcinoma, thereby controlling the self-renewal, differentiation, and in vivo tumorigenicity of cancer cells." (PMID 39239559, 2024). "Therefore, it is suggested that ITGB1 can serve as a marker for the stemness of head and neck squamous cell carcinoma." (PMID 39239559, 2024). "From head and neck squamous cell carcinoma (HNSCC) parent cell lines, ITGB1 (+) cells were sorted, and it was found that in mouse xenograft models, ITGB1 (+) cells exhibited greater tumorigenicity compared to ITGB1 (−) cells." (PMID 39239559, 2024).
leukemia (8 papers, 2012 to 2023). A malignant (clonal) hematologic disorder, involving hematopoietic stem cells and characterized by the presence of primitive or atypical myeloid or lymphoid cells in the bone marrow and the blood. "We first validated CXCR4 and ITGB1 which are well-known to influence the leukemia-niche interaction and dropped out in both ALL samples." (PMID 37422628, 2023). "The migration and invasion of controlled leukemia cells, the leukemia cells of the EV group, and the leukemia cells of silent (Si)-ITGB1 were detected." (PMID 34733839, 2021). "Subsequently, AMD3100 was added to the co-culture system, which weakened the expression of ITGA5 and ITGB1 in leukemia cells (P < 0.05)." (PMID 34733839, 2021). "In addition, up-regulation of ITGB1 partially weaken the inhibitory effect of AMD3100 on the adhesion of leukemia cells under AMD3100 treatment (P < 0.05)." (PMID 34733839, 2021). "After AMD3100 treating, the migration and invasion numbers of leukemia cells in the control group and the EV group were obviously decreased, but up-regulation of ITGB1 in leukemia cells could partially reverse the inhibition effect of AMD3100 (P < 0.05)." (PMID 34733839, 2021). "Further verification by 3D co-culture system showed that the results seemed to be consistent with the fluorescence quantitative method, suggesting that down-regulating the ITGB1 in leukemia cells might effectively reduce the interaction between MSCs with CAF-like phenotype and ALL cells." (PMID 34733839, 2021). "ITGB1 and ITGA4 were expressed as very late antigen-4 (VLA-4) in most of the cell lines, but ITGB4 and ITGA6 were expressed in all three leukemia cell lines and in the two primary EVI1high leukemia cell lines." (PMID 22295105, 2012). "Down-regulating the ITGB1 on leukemia cells could significantly reduce the adhesion, migration and invasion effects of MSCs with CAF-like phenotype on leukemia cells." (PMID 34733839, 2021). "ITGB1, ITGB3, ITGA4, and ITGA5 were expressed in five of the six leukemia cell lines, and ITGB4 and ITGA6 were specifically expressed in the three EVI1high leukemia cell lines." (PMID 22295105, 2012). "Finally, within CSF + LM group, differential protein profiles were observed between leukemia and lymphoma (such as FCGR1, CR2, ABL1, PTPRC, SELP, ITGB1, COL9A3 or ITGAX), which could subtype the CSF + LM depending on the primary tumor." (PMID 35053611, 2022).
lung adenocarcinoma (8 papers, 2017 to 2024). A carcinoma that arises from the lung and is characterized by the presence of malignant glandular epithelial cells. "We utilized the KRAS-mutated human lung adenocarcinoma cell lines A549 and H358 and deleted ITGB1 (integrin β1) using CRISPR/Cas9." (PMID 35763345, 2022). "A previous study of ITGB1 demonstrated its association with migration activity, invasion and wound healing in an in vitro experiment of lung adenocarcinoma." (PMID 28871224, 2017). "We concede that ITGB1 and EIF2AK3 have limitations in predicting the prognosis of lung adenocarcinoma." (PMID 36178365, 2022). "Human EIF2AK3 and ITGB-1 specific primers were designed and total RNA was extracted by NCI-H1975 (human lung adenocarcinoma cell) and BEAS-2B (human normal lung epithelial cell)." (PMID 36178365, 2022). "In lung adenocarcinoma, only the EAM gene ITGB1 and the desmosome gene DST significantly converged towards co-occurrence (p value = 0.021)." (PMID 29348685, 2018).
Obesity (8 papers, 2020 to 2025). Accumulation of substantial excess body fat. "ITGB1 may play central roles in all DEGs and have a close relationship with the development of obesity, T2DM, and its complications." (PMID 33149760, 2020). "BMI-predictive proteins included established obesity markers and obesity-related proteins, including adiponectin, CRP, IGFBP1, IGFBP2, PRG4, SHBG, apolipoproteins (APOA4, APOF) and inflammatory response proteins (A2M, APCS, LBP, HSPG2, HP, AOC3, ITGB1, VNN1)." (PMID 39972214, 2025).
atherosclerosis (7 papers, 2015 to 2025). A disease characterized by the build-up of fatty material and calcium deposition in the arterial wall resulting in partial or complete occlusion of the arterial lumen. "In atherosclerosis, ECs communicated extensively with pericyte cells and SMCs through LAMININ (LAMA5-(ITGA1+ITGB1), LAMA5-(ITGA7+ITGB1), LAMB2-(ITGA6+ITGB4), LAMB2-(ITGA6+ITGB1)) and COLLAGEN (COL4A1-(ITGA1+ITGB1), COL4A2-(ITGA1+ITGB1)) pathways." (PMID 40225569, 2025).
fibrosis (7 papers, 2016 to 2025). the formation of excess fibrous connective tissue in an organ or tissue in a reparative or reactive process. "We emphasized the critical role of ITGB1 in regulating mechanical stress-induced fibrosis of the diaphragm during mechanical ventilation with high-PEEP application." (PMID 41154695, 2025). "Inactivation of ITGB1 leads to preservation of normal renal function and suppression of fibrosis in polycystic kidney disease." (PMID 33299380, 2020). "In fibrosis, COL10A1 interacts with the integrin subunit β1 (ITGB1), which not only strengthens cell–ECM adhesion but also triggers the TGFβ signaling pathway." (PMID 40002743, 2025). "Our data linking dendritic cells to fibroblasts, smooth muscle cells and pericytes by potential ITGB1 signaling is novel and suggests an important role for these cells in the pathological hypertrophy, cardiac fibrosis and vascular abnormalities seen in nonobstructive HCM." (PMID 36237479, 2022).
Alzheimer disease (6 papers, 2014 to 2025). A progressive, neurodegenerative disease characterized by loss of function and death of nerve cells in several areas of the brain leading to loss of cognitive function such as memory and language. "Another proteomics study on brain-derived EVs including neurons, astrocytes, oligodendrocytes, and microglia, put forward that ADEVs were highly enriched in a specific hub protein, the integrin-β1 (ITGB1) associated with Alzheimer’s disease pathology." (PMID 36140248, 2022).
endometriosis (6 papers, 2015 to 2024). The growth of functional endometrial tissue in anatomic sites outside the uterine body. "Moreover, we found that ITGB1 is overexpressed in the endometrium of endometriosis patients." (PMID 26357653, 2015). "The results of phenolyzer analysis showed that ITGB1, HDAC2 and LAMB1 were the top three important genes in endometriosis." (PMID 34586697, 2021). "We further detected differential expression of ITGB1 in endometrium with or without endometriosis by quantitative RT-PCR." (PMID 26357653, 2015). "ITGB1 has been reported as deregulated in endometrial disease with increased expression of ITGB1 detected in a small number of endometrial samples from women with endometriosis compared to women without the disease." (PMID 30061686, 2018).
gastric adenocarcinoma (6 papers, 2016 to 2024). "The expression of ITGB1 was considerably higher in gastric adenocarcinoma than in normal tissues, and it was also higher in the tumor tissues of individuals with advanced cancer (P < 0.05)." (PMID 38402311, 2024). "We used serum-starved gastric adenocarcinoma epithelial cells (AGS) after 30 min of serum addition, at which point a high amount of ITGB1 was present on the surface of the cells." (PMID 26983895, 2016).